ABCA1 (ATP binding cassette subfamily A member 1)
Diseases named in the same sentence as ABCA1 in open-access papers (continued):
Sharing a sentence is not in itself a finding about the gene and the disease.
atherosclerosis (continued). "The direct role of ABCA1 expression and ANXA1 release in atherosclerosis has been unclear." (PMID 32894039, 2020). "We have recently shown that PLG is an effective sterol acceptor through ABCA1, and this could be the mechanism by which PLG contributes to atherosclerosis." (PMID 30622162, 2019). "Reduction in ABCA1 and consequently of cholesterol efflux, as well as increased abundance of TREM-1 in rafts, are recognized factors promoting accumulation of cholesterol in macrophages and inflammation, two key elements in pathogenesis of atherosclerosis." (PMID 31344124, 2019). "ABCA1, ABCG1, ACAT1, and CD36 are positive or negative regulators of atherosclerosis." (PMID 30105261, 2018). "Rather, lipid-free ApoAI stimulates ABCA1 removal of excess cellular cholesterol via the formation of nascent HDL particles, thereby suppressing signaling that would otherwise lead to activation and/or recruitment of immune cells to the atherosclerosis plaque." (PMID 29545616, 2018). "Recently, the pharmacologic suppression of hepcidin has been shown to increase the expression of ABCA1 and ABCG1 and lipid efflux via the macrophage-specific expression of cholesterol efflux transporters and to reduce foam cell formation and atherosclerosis in vivo and vitro." (PMID 30373612, 2018). "Although few studies have started to focus on its potential in atherosclerosis prevention, no studies have investigated its effects on regulating ABCA1." (PMID 29970865, 2018). "ABCA1 overexpression in C57BL/6 mice on a high‐cholesterol diet results in an atheroprotective lipoprotein profile and decreased atherosclerosis, but ABCA1 overexpression in Apoe KO mice led to increased atherosclerosis." (PMID 27396856, 2016). "Thus, ABCA1- and ABCG1-driven cholesterol efflux in macrophages was a key regulator in anti-atherosclerosis." (PMID 27328813, 2016). "Mice lacking ABCA1 are prone to atherosclerosis when challenged with a high-fat diet, suggesting a critical role for ABCA1 in atheroprotection." (PMID 27295295, 2016). "Our study affirmed the role of ABCA1 in the atherogenic process and verified a mechanism by which CRH as a stress hormone accelerates macrophage foam cell formation, which is a pivotal step in atherosclerosis." (PMID 26110874, 2015). "Changes in cellular SM levels may be involved in regulating the function of ABCA1 and ABCG1, and in the development of atherosclerosis." (PMID 25302608, 2014). "Mir-144-3p targeting ABCA1, the doorkeeper of RCT, resulted in impaired cholesterol efflux and boosted inflammatory response, which effectively accelerated the occurrence and progression of atherosclerosis in apoE−/− mice fed HFD." (PMID 24733347, 2014). "PON1 also contributes to the attenuation of atherosclerosis development by leading to the formation of lysophosphatidylcholine, which, in turn, stimulates HDL binding and HDL-mediated macrophage cholesterol efflux via the ABCA1 transporter." (PMID 23691522, 2013). "The literature indicates that induction of ABCA1 and ABCG1 expression by PPAR activation may play a role in preventing atherosclerosis by improving cholesterol homeostasis and HDL synthesis." (PMID 22919365, 2012). "It has been reported that mice lacking ABCA1 expression in macrophages developed accelerated atherosclerosis." (PMID 22984960, 2012). "Increased macrophage ABCA1 expression might thus counteract the effect of ABCA7 deletion in foam cell formation and atherosclerosis." (PMID 22403608, 2012). "Since MPO-oxidized apolipoprotein A-I (apoA-I) impairs the cellular cholesterol efflux by ABCA1, INV-315 may retard atherosclerosis development via inhibition of HDL oxidation." (PMID 23251382, 2012). "Taken together, these findings suggest that all three transporters involving macrophage ABCA1, ABCG1 and SR-BI may exert protective functions in atherosclerosis." (PMID 22984960, 2012).
atherosclerosis (continued). "As TGF-β downregulates scavenger receptors, such as scavenger receptor type A (SR-A) I/II and CD36, and upregulates ATP-binding cassette (ABC) transporters, ABCA1 and ABCG1, TGF-β is also thought to have protective effects against the development of atherosclerosis." (PMID 21199582, 2011). "In the control group, there were no atherosclerosis plaques and immunohistochemical staining in aortic walls for ABCA1 and SR-B1." (PMID 22078494, 2011). "In the mouse model, macrophage specific knockout of ABCA1 does not have a significant effect on HDL plasma levels but results in increased atherosclerosis." (PMID 19348677, 2009). "Abca1, Abcg5 and Abcg8 belong to the family of ABC transporters, which can mediate secretion of excessive cholesterol into bile and play important roles in consequent gallstones or atherosclerosis." (PMID 19835623, 2009). "It has been reported that ABCA1 is absent in cells of atherosclerotic lesions, which demonstrates that the tight regulation of this efflux system is critical to atherosclerosis development." (PMID 19040724, 2008). "The current study indicated that ROS-GLY protected against the progression of NAFLD and atherosclerosis in dyslipidemic rats via modulation of lipid profile, oxidative stress, pro-/anti-inflammatory cytokines, hepatic lncRNA-H19/miR-130a/PPAR-γ, and aortic PPAR-γ/LXRα/ABCA1 signaling pathways." (PMID 41611768, 2026). "Snail2 promoted atherosclerosis development by enhancing the transformation of VSMCs toward an inflammatory phenotype by activating the cyclooxygenase-2 (COX-2)/prostaglandin E2 (PGE2) pathway and suppressing cholesterol efflux by reducing ABCA1 and ABCG1 promoter expression in VSMCs." (PMID 40176913, 2025). "In addition, the absence of macrophage ABCA1/G1 promotes atherosclerosis by increasing pro-inflammatory cytokine production in atherosclerotic plaques." (PMID 40867523, 2025). "The expression of the ATP-binding cassette transporter A1 (ABCA1) has been shown to link cholesterol accumulation with inflammatory responses, suggesting that targeting lipid metabolism may have therapeutic implications for managing atherosclerosis." (PMID 39941147, 2025). "Notably, the role of these downstream genes (except ABCA1) in atherosclerosis is not direct but indirectly affects atherosclerosis by regulating other genes or proteins." (PMID 40176913, 2025). "Thus, the role of ABCG1 in macrophages in atherosclerosis, in contrast to ABCA1, is still not sufficiently clear and requires new studies." (PMID 39857239, 2024). "LRP1 has a protective function against atherosclerosis through modulating ATP-binding cassette A1 (ABCA1) expression via extracellular regulated protein kinases 1/2 (ERK1/2)/cytosolic phospholipase A2 (cPLA2/)arachidonic acid, an inhibitor of ABCA1 expression driven by liver X receptors (LXR)." (PMID 39524227, 2024). "During obesity, the expression of ABCA1 can be inhibited in human macrophages and ABCA1/ABCG1 in murine macrophages by miR-23a-5p and miR-33a-5p, which leads to impaired reverse cholesterol transport into HDL, accelerated atherosclerosis, formation of foam cells and NAFLD." (PMID 39063184, 2024). "Interestingly, we report for the first time the role of fucoidan in regulating ABCA1 in THP-1 macrophages, which could be an effective treatment route for atherosclerosis." (PMID 38001931, 2023). "Moreover, silencing or inhibition of miR-33 could prevent its suppression of ABCA1 and ABCG1 which may in turn inhibit atherosclerosis progression." (PMID 36361845, 2022). "However, it is largely unknown whether and how asprosin has an effect on ABCA1 and ABCG1 expression and atherosclerosis." (PMID 35902881, 2022). "Thus, ABCA1 and ABCG1, which are a link in reverse cholesterol transport, along with HDL demonstrate involvement in the pathogenesis of COPD and its comorbid links with atherosclerosis." (PMID 35897703, 2022).
atherosclerosis (continued). "Regarding the ABCA1 and ABCG1 induction mechanisms, liver X receptor (LXR) agonists are the most well-identified transcription factors to stimulate ABCG1 and ABCA1 expression, resulting in promotion of cholesterol efflux from macrophages, and eventually protection against atherosclerosis in mice." (PMID 34445501, 2021). "We analyzed these microRNAs and selected those that have the possibility to regulate atherosclerosis and evolutionarily conserved, including, miR-30d-3p and miR-140-3p, which had conserved binding sites with mmu_circRNA_37699 (circRNA KHDRBS1) and mmu_circRNA_36781 (circRNA ABCA1)." (PMID 34307490, 2021). "Excessive intracellular accumulation of cholesterol in macrophages due to a decrease in the transport function of ABCA1 contributes to the initialization of NLRP3 (NLR family pyrin domain containing 3) inflammation, which makes a significant contribution to the progression of atherosclerosis." (PMID 34201488, 2021). "Thus, the closely intertwined disorders of ABCA1-mediated cellular lipid efflux, homeostasis of membrane lipid rafts, and inflammatory activation of macrophages make a significant contribution to the pathogenesis of COPD and atherosclerosis." (PMID 34201488, 2021). "Extensive evidence suggests that ABCA1 plays a critical role in reverse cholesterol transport by HDL biogenesis, where HDL facilitates cholesterol transportation to the liver from the peripheral tissues and thus inhibits foam cell formation and atherosclerosis." (PMID 33066695, 2020). "Notably, these macrophages were shown to have significantly decreased activity of ATP-binding cassette transporter A1 (ABCA1), a lipid transporter essential for cholesterol efflux, thus potentially leading to accelerated development of foam cells and progression of atherosclerosis." (PMID 32887404, 2020). "They analyzed the promoter methylation of ATP binding cassette subfamily A member 1 (ABCA1), TIMP metallopeptidase inhibitor 1 (TIMP1), and acetyl-CoA acetyltransferase 1 (ACAT1) and observed significant alterations in the peripheral blood of atherosclerosis patients." (PMID 31649728, 2019). "LOX-1 mediated suppression of ABCA1 in macrophages could be reversed by TZDs, which improved the reverse cholesterol transport and prevented the foam cell formation and ox-LDL accumulation on the arterial wall in the development of atherosclerosis." (PMID 31354796, 2019). "Therefore, reduction of TTC39B and enhancement of the LXRα-ABCA1/ABCG5/8 pathway was at least partly responsible for the inhibitory effect of EGCG on the anti-inflammatory and lipid-regulatory effects in high-fat-induced atherosclerosis." (PMID 29593532, 2018). "The ATP-binding cassette transporters A1 (ABCA1) played a critical role in reverse cholesterol transport, which mediates the rate-controlling step in HDL particle formation, and substantially affects whole body cholesterol and HDL metabolism and the development of atherosclerosis." (PMID 27916850, 2016). "Thus, the activation of cholesterol efflux pathways targeting ABCA1 and ABCG1 may prove to be novel therapeutic approaches to the treatment of atherosclerosis." (PMID 25673178, 2015). "Our data showed that mRNA levels of ABCA1 and ABCG1 were increased after the treatment of NLRP3i, suggesting that NLRP3 gene silencing could be a potentially therapeutic mean to increase macrophage cholesterol efflux for the prevention of atherosclerosis." (PMID 24999295, 2014).
atherosclerosis (continued). "Since the results herein our report do show that inhibiting miR-33a-5p does promote ABCA1-dependent cholesterol efflux in cultured MLC, these findings demonstrate, proof-of-concept, that specific inhibition of miR-33a-5p in MLC may have therapeutic implications in treating atherosclerosis." (PMID 38535619, 2024). "However, unlike ABCA1, the deficiency of which is associated with Tangier disease characterized by low HDL levels and early development of atherosclerosis, there are no data on a similar pattern for ABCG1 deficiency, which is probably compensated for by the ABCA1 function." (PMID 39857239, 2024). "Furthermore, miR-486-5p was shown to reduce ABCA-1 expression in macrophages that we reproduced through our studies of BMDM-HG-exo, which in this context could contribute to atherosclerosis acceleration in Apoe−/− mice treated with BMDM–HG-exo, and atherosclerosis in diabetic patients." (PMID 34381972, 2021). "Therefore, DNA methylation of ABCA1 and ABCG1 could be involved in atherosclerosis development." (PMID 34837967, 2021). "While our findings in vitro suggest that rHDL + T1317 combination therapy can upregulate ABCA1 and ABCG1 at the mRNA and protein level as well as increase TC efflux when compared to either drug alone, we wanted to confirm whether these findings confer a greater anti-atherosclerosis effect in vivo." (PMID 33390931, 2020). "Interestingly, stimulation of macrophage mitochondrial ATP production resulted in the increase of ABCA1 expression and cholesterol efflux with a concomitant decrease in aortic sinus lesion area in atherosclerosis-prone mice, despite no changes in HDL cholesterol." (PMID 30174957, 2018). "Interestingly, expression of Lxrα and Abca1 is 5-fold higher in the thoracic aorta, a region more resistant to the development of atherosclerotic lesions, as opposed to the aortic root, a region more atherosclerosis-prone." (PMID 30087224, 2018). "Moreover, mRNA levels of ABCA1 and ABCG1 were increased after the treatment of NLRP3i, suggesting that NLRP3 gene silencing could be a potentially therapeutic mean to increase macrophage cholesterol efflux for the prevention of atherosclerosis." (PMID 27239478, 2016). "While the biochemical events in the RCT pathway have been studied thoroughly, it is still not clear how changes in the functioning of ABCA1, ABCG1, and SCARB1 affect atherosclerosis progression." (PMID 34940525, 2021). "Liver X receptors (LXR) directly activate ABCA1, and experimental and clinical studies support potentially beneficial effects of LXR agonism to decrease foam cell formation and atherosclerosis in non-CKD settings." (PMID 29374468, 2018). "It is widely recognized that macrophage cholesterol efflux mediated by the ATP-binding cassette transporter A1 (ABCA1) constitutes the initial and rate-limiting step of reverse cholesterol transport (RCT), displaying a negative correlation with the development of atherosclerosis." (PMID 38139111, 2023). "ABCA1 and ABCG1 knockout specific to macrophages, and not in hematopoietic stem and multipotential progenitor cells, still leads to monocytosis and neutrophilia and increased atherosclerosis." (PMID 35052806, 2022).
Tangier disease (132 papers, 2005 to 2026). "A rare form of peripheral neuropathy in Tangier disease (TD) patients is associated with autosomal recessive mutations in ABCA1." (PMID 41750400, 2026). "Tangier disease (TD) is a rare, autosomal recessive genetic disorder associated with a deficiency in cellular cholesterol and phospholipid export mediated by the ATP binding cassette transporter A1 (ABCA1)." (PMID 40037526, 2025). "Background and aims: Tangier Disease (TD) is a rare genetic disorder caused by mutations in the ABCA1 gene, resulting in low HDL levels and cholesterol buildup." (PMID 40542608, 2025). "Tangier disease, caused by an ABCA1 gene mutation, presents with extremely low HDL levels, peripheral neuropathy, hepatosplenomegaly, and corneal opacification that does not affect vision." (PMID 40937252, 2025). "Tangier disease is a rare genetic disorder caused by a deficiency in the ABCA1 gene, resulting in impaired metabolism of high-density lipoprotein (HDL) cholesterol." (PMID 40330358, 2025). "Tangier disease results from either homozygosity or compound heterozygosity for pathogenic variants in ABCA1 and is characterized by extremely low HDL-C levels, often below 5 mg/dl (0.13 mmol/l)." (PMID 40617357, 2025). "Mutations in ABC transporters are etiological drivers of rare monogenic diseases with a cardiovascular component, such as Pseudoxanthoma Elasticum caused by mutations in ABCC6 and Tangier disease caused by mutations in ABCA1." (PMID 41252867, 2025). "ABCA1: Heterozygous genetic loss-of-function variants in the ABCA1 gene causes familial hypoalphalipoproteinemia; bi-allelic loss-of-function ABCA1 causes Tangier disease." (PMID 40004987, 2025). "Various ABCA1 mutations found in patients with Tangier disease cause misfolding of the ABCA1 protein." (PMID 40619002, 2025). "Certain genetic variants causing Tangier disease have previously been demonstrated to impair the translocation of ABCA1 to the cell membrane." (PMID 38052254, 2024). "Biallelic variants in ABCA1 are the genetic basis of autosomal recessive Tangier disease (MIM: 205400) characterized by reduced levels of plasma high density lipoproteins (HDL)." (PMID 38816421, 2024). "4-PBA has been shown to be capable of restoring functionality in transport-defective ABCA1, including the Tangier disease-associated variant p.Y1767D." (PMID 38052254, 2024). "Genetic variants affecting ABCA1 functionality is evident in Tangier disease (OMIM #205400) caused by biallelic loss-of-function variants." (PMID 38052254, 2024). "These transporters are linked to diseases like cystic fibrosis (ABCC7/CFTR), Tangier disease, cardiovascular disease (ABCA1), retinitis pigmentosa (ABCA4), and more." (PMID 39238930, 2024). "Homozygous or compound heterozygous mutations in the ABCA1 gene cause Tangier disease (TGD) (OMIM, 205400)." (PMID 37510094, 2023). "The findings from the present study expand the mutational spectrum of the ABCA1 gene in Tangier disease and emphasize the important complement of whole-exome sequencing (WES) studies in establishing precise clinical diagnosis of this rare condition." (PMID 37048678, 2023). "Tangier disease (TD) is a rare autosomal recessive disorder caused by homozygous or compound heterozygous variants in the ABCA1 gene which encodes a cell plasma membrane cholesterol transporter." (PMID 37048678, 2023). "Loss-of-function mutation in the gene encoding ABCA1 causes the autosomal recessive genetic disorder Tangier disease associated with very low HDL-C levels and severe hypertriglyceridemia." (PMID 37375802, 2023). "It had previously been shown that levels of NPC1 increase in Tangier disease cells, potentially in an attempt to rebalance cholesterol transport pathways when ABCA1 is deficient." (PMID 37844193, 2023).